MOAP1 (modulator of apoptosis 1)
Description:
Retrotransposon-derived protein that forms virion-like capsids (By similarity). Acts as an effector of BAX during apoptosis: enriched at outer mitochondria membrane and associates with BAX upon induction of apoptosis, facilitating BAX-dependent mitochondrial outer membrane permeabilization and apoptosis. Required for death receptor-dependent apoptosis. When associated with RASSF1, promotes BAX conformational change and translocation to mitochondrial membranes in response to TNF and TNFSF10 stimulation. Also promotes autophagy: promotes phagophore closure via association with ATG8 proteins. Acts as an inhibitor of the NFE2L2/NRF2 pathway via interaction with SQSTM1: interaction promotes dissociation of SQSTM1 inclusion bodies that sequester KEAP1, relieving inactivation of the BCR(KEAP1) complex.
Synonyms: MAP-1; PNMA4
Tractability: Antibody: UniProt places it where antibodies can reach, with medium confidence. PROTAC: UniProt records ubiquitination sites on it; ubiquitination databases record sites on it; its protein half-life has been measured.
Gene: Protein-coding gene on chromosome 14 (93,182,176 to 93,184,930, reverse strand). Ensembl gene ENSG00000165943.
Subcellular location: Cytoplasm, cytosol; Mitochondrion outer membrane; Extracellular vesicle membrane
Subcellular location (Human Protein Atlas): Nucleoplasm; Cell Junctions
Gene Ontology:
Molecular function: protein binding; ubiquitin protein ligase binding
Biological process: apoptotic signaling pathway; extrinsic apoptotic signaling pathway in absence of ligand; extrinsic apoptotic signaling pathway via death domain receptors; intrinsic apoptotic signaling pathway in response to DNA damage; positive regulation of apoptotic process; positive regulation of autophagosome assembly; positive regulation of release of cytochrome c from mitochondria; protein insertion into mitochondrial membrane; regulation of apoptotic process
Cellular component: cytoplasm; cytosol; mitochondrial outer membrane; mitochondrion
Genetic constraint (gnomAD): Loss-of-function variants: 2 observed, 2.38 expected, observed/expected ratio (o/e) 0.84, 90% interval 0.32 to 1.83. That is too few expected variants to judge how well the gene tolerates losing a copy. Missense variants: 385 observed, 444.96 expected, observed/expected ratio (o/e) 0.87, 90% interval 0.8 to 0.94. Synonymous variants: 150 observed, 172.14 expected, observed/expected ratio (o/e) 0.87, 90% interval 0.76 to 1.
Homologues: Orthologues: chimpanzee MOAP1 (99% identical), macaque MOAP1 (98% identical), mouse Moap1 (77% identical), rat Moap1 (77% identical). Paralogues in human: PNMA1 (58% identical), PNMA2 (46% identical), PNMA3 (45% identical), PNMA5 (45% identical), PNMA6A (40% identical), PNMA6E (38% identical), PNMA6F (36% identical), PNMA8A (24% identical), ZCCHC12 (20% identical), ZCCHC18 (20% identical), PNMA8B (19% identical), PNMA8C (15% identical), and 1 more.
Diseases named in the same sentence as MOAP1 in open-access papers:
MOAP1 is named in the same sentence as 32 diseases in open-access papers, as found by Europe PMC text mining. Sharing a sentence is not in itself a finding about the gene and the disease. The quoted sentences say what the papers report.
lung carcinoma (7 papers, 2015 to 2024). "For example, MOAP1 is involved in the progression, invasion, metastasis, and chemo-sensitization of various cancers, including lung cancer, colorectal cancer, and breast cancer." (PMID 35269511, 2022). "used a weighted gene co-expression network analysis screening method to identify four key genes that are shared with OSA and lung cancer, namely modulator of apoptosis 1 (MOAP1), chromobox 7 (CBX7), platelet-derived growth factor subunit B (PDGFB), and mitogen-activated protein kinase 3 (MAP2K3)." (PMID 38605948, 2024). "Thus, miR-25 antagomir can promote MOAP1 expression and thus inhibit lung cancer growth in a mouse xenograft model." (PMID 35269511, 2022). "MOAP1 is one of the genes to mediate lung cancer-related miRNAs and lung cancer." (PMID 35269511, 2022). "Thus, the roles of MOAP1 in various cancers and related biological mechanisms have been widely studied, among which lung cancer, colorectal cancer (CRC), and breast cancer are probably the most well studied." (PMID 35269511, 2022). "It was reported recently that miR-25 can target MOAP1 mRNA in lung cancer cells." (PMID 30992737, 2019). "Myc-MOAP-1 was transiently expressed in DAOY medulloblastoma cells, SKOV3 (stable expression, ovarian cancer), or H1299 (stable expression, lung cancer) and transiently in HCT116 colon cancer cells." (PMID 26269600, 2015). "That is, a few miRNAs can regulate MOAP1 and BAX, which may contribute to the apoptosis of lung cancer cells." (PMID 35269511, 2022). "miR-25 was reported to inhibit apoptosis in lung cancer by targeting RGS3 and MOAP1." (PMID 30992737, 2019).
colorectal cancer (6 papers, 2020 to 2024). A primary or metastatic malignant neoplasm that affects the colon or rectum. "Mechanistically, STAT3 increased miR-572 levels to inhibit the expression of modulator of apoptosis-1, leading to enhanced cell growth, migration, and invasion in colorectal cancer." (PMID 38273295, 2024). "Elevated miR-572 expression and downregulation of modulator of apoptosis-1 were observed in colorectal cancer with high expression of STAT3." (PMID 38273295, 2024). "Activating the Wnt/β-catenin signaling pathway and inhibiting mitochondrial apoptosis by directly inhibiting FBXW7 and MOAP1 are helpful to the resistance of EMT and chemotherapy drugs in colorectal cancer." (PMID 38188683, 2023). "Exosome-derived miR-92a-3p from CAFs encourages EMT by targeting F-box with 7 tandem WD40 (FBXW7) and modulator of apoptosis 1 (MOAP1), which further promotes the resistance to fluorouracil and oxaliplatin of colorectal cancer cells (CRCs)." (PMID 36359776, 2022). "However, a possible explanation could involve the methylation status, where the downregulation of MOAP1 is independent of miR-1228 regulation in colorectal cancer due to epigenetic modifications in RASSF1A." (PMID 32244548, 2020).
breast carcinoma (3 papers, 2015 to 2022). "As a result, MOAP1, its upstream genes, and miRNAs play critical roles in the progression, invasion, and migration of breast cancer." (PMID 35269511, 2022). "Breast cancer patient data were analyzed based on levels of MOAP-1 expression with relation to various clinical and pathological features of interest as shown." (PMID 26269600, 2015). "Detailed analysis revealed a steady and significant decrease in MOAP-1 expression that correlated with increasing breast cancer aggressiveness in luminal B, Her2-amplified, and triple-negative subtypes." (PMID 26269600, 2015). "Breast cancer microarray expression data generated from 176 primary and treatment-naive breast cancer samples and 10 normal breast tissue samples revealed that MOAP-1 expression was reduced 5-fold in breast tumor samples." (PMID 26269600, 2015). "Finally, a recent study suggested that the tricistronic expression of MOAP1, BAX, and RASSF1A enhances chemo-sensitization in breast cancer cell lines." (PMID 35269511, 2022).
ovarian carcinoma (3 papers, 2015 to 2022). A malignant neoplasm originating from the surface ovarian epithelium. "As a novel ubiquitin ligase for the proapoptotic protein modulator of apoptosis protein 1 (MOAP-1, also known as MAP-1), UBR5 influences ovarian cancer cell cisplatin resistance by mediating MOAP-1 ubiquitination and degradation through cooperation with Dyrk2 kinase." (PMID 35582023, 2021).
neuroblastoma (2 papers, 2015 to 2019). Neuroblastoma (NB) is the most common solid, extracranial childhood tumor. "We explored MOAP-1 mRNA expression in 88 neuroblastoma patients in collaboration with Dr. Rogier Versteeg (University of Amsterdam, Netherlands)." (PMID 26269600, 2015). "This is supported by in vitro observations that over-expression of MOAP-1 does not induce apoptosis in SY5Y human neuroblastoma cells and Neuro2a mouse neuroblastoma cells." (PMID 30003515, 2019).
bladder cancers (1 paper, 2016). "Analysis of data obtained from TCGA reveals evidence for the reduction of MOAP-1 expression in numerous cancers with the lung, cervical, colorectal, rectal, bladder cancers and glioblastoma (red tagged data points)." (PMID 27294960, 2016).
brain cancer (1 paper, 2015). A primary or metastatic malignant neoplasm affecting the brain. "Because MOAP-1 is frequently down-regulated in brain cancer, it may therefore have a role in inhibiting malignancy formation in brain tissues." (PMID 26269600, 2015).
Cerebral ischemia (1 paper, 2022). Restriction of arterial blood supply to the brain associated with insufficient oxygenation to support the metabolic requirements of the tissue. "In the mouse transient middle cerebral artery occlusion (tMCAO) model, cerebral ischemia causes the MOAP1/BAX association, activating the MOAP1-dependent apoptosis cascade." (PMID 35269511, 2022). "BAX ablation might be a feasible direction to control cerebral ischemia, which makes MOAP1 critical in cerebral ischemia since it can regulate BAX and BCL2 in neurons." (PMID 35269511, 2022).
chordoma (1 paper, 2013). Chordomas are rare malignant tumors arising from embryonic remnants of the notochord in axial skeleton. "MiR-1228 has been found to be upregulated in many malignancies and is involved in the inhibition of cellular apoptosis by repressing MOAP1 expression; however, it was downregulated in our study and in previous miRNA study on chordomas." (PMID 23826111, 2013).
depression (1 paper, 2019). "In conclusion, MOAP-1−/− mice exhibit increased immobility times when compared to WT controls in FST and TST, both are acute stress models of depression, probably caused by impaired serotonergic functions." (PMID 30003515, 2019). "While both BAX−/− and MOAP-1−/− mice showed depression-like behavior, they differ in another aspect." (PMID 30003515, 2019). "Additional studies would be necessary to more fully understand the role of MOAP-1 in depression." (PMID 30003515, 2019). "Thus, it may be speculated that the depression-like behavior of the MOAP-1−/− mice may be related to the reduced BDNF which in turn blunted the serotonergic stress response in the DRN." (PMID 30003515, 2019).
Hepatic fibrosis (1 paper, 2021). The presence of excessive fibrous connective tissue in the liver. "In addition, up-regulation of genes involved in tissue injury and hepatic fibrosis (Adora1), caspase-dependent apoptosis (Moap1), and oxidative stress and antioxidant defense (Ephx2 and Oxr1) was identified only in the liver treated with Zn ions." (PMID 33567653, 2021).
medulloblastoma (1 paper, 2015). A malignant, invasive embryonal neoplasm arising from the cerebellum. "To carry out these assays, we selected cancer cell lines with reduced or absent MOAP-1 expression (DAOY medulloblastoma cells, SKOV3 and H1299) or with a detectable amount of MOAP-1 (HCT116 cells)." (PMID 26269600, 2015).
myeloma (1 paper, 2015). "Interestingly, parathyroid, myeloma, prostate/ovarian/cervical (that is the reproductive organs), and gastric datasets revealed elevated expression of MOAP-1 to suggest that MOAP-1 expression can vary widely and may have differential function in numerous tissues." (PMID 26269600, 2015).
non-small cell lung carcinoma (1 paper, 2019). A group of at least three distinct histological types of lung cancer, including non-small cell squamous cell carcinoma, adenocarcinoma, and large cell carcinoma. "MiR-25 promotes cell proliferation and inhibits cell apoptosis by directly targeting MOAP1 in non-small cell lung cancer." (PMID 31064356, 2019).
pancreatic cancers (1 paper, 2016). "Data analysis from TCGA suggests that changes in MOAP-1 and RASSF1A do not occur in a random fashion in breast, lung and pancreatic cancers that have a p-value of <0.05." (PMID 27294960, 2016).
Parkinson disease (1 paper, 2022). A progressive degenerative disorder of the central nervous system characterized by loss of dopamine producing neurons in the substantia nigra and the presence of Lewy bodies in the substantia nigra and locus coeruleus. "It is well known that MOAP1 directly binds to BAX, which suggests that MOAP1 may play a role in Parkinson’s disease." (PMID 35269511, 2022).
thyroid cancer (1 paper, 2016). "In addition, we can observe a positive correlation between RASSF1A and MOAP-1 in breast, colorectal and thyroid cancers upon empirical testing by qPCR." (PMID 27294960, 2016).
viral infection (1 paper, 2023). "Virus-encoded miRNAs also protect cells from DNA damage and apoptosis caused by viral infection, e.g., human herpesvirus-8 miR-K9 reduced the expression of cleaved caspase-3 and caspase-7 and HCMV-encoded miR-UL70-3p inhibited apoptosis by suppressing expression of the pro-apoptotic gene MOAP1." (PMID 38136848, 2023).
cancer (14 papers, 2012 to 2026). A tumor composed of atypical neoplastic, often pleomorphic cells that invade other tissues. "Due to its critical role in a few of disease-associated pathways, MOAP1 is associated with many diseases such as cancers and neurological diseases." (PMID 35269511, 2022). "Previous studies have suggested that MOAP1 is highly associated with the apoptosis pathway, one of the most critical pathways and hallmarks in cancer." (PMID 35269511, 2022). "In this study, we introduced MOAP1 and its biological functions and reviewed the associations between MOAP1 and a few diseases including cancers, neurological diseases, and other diseases such as inflammation and heart diseases." (PMID 35269511, 2022). "The results obtained from this meta-analysis indicate that MOAP-1 expression is markedly reduced in multiple types of human cancers, especially in the brain, breast, blood, skin, and lung suggesting that loss of MOAP-1 is important for tumorigenesis to occur." (PMID 26269600, 2015). "Future investigations will be required in order to determine the cause(s) underlying MOAP-1 expression changes in human cancer." (PMID 22745908, 2012). "Among the PNMA genes, MOAP1 is probably the most important because it not only plays a central role in mitochondria and death receptor-mediated apoptosis, but also is associated with many diseases like cancer." (PMID 35269511, 2022). "Frequent loss of MOAP-1 expression, in at least some cancers, appears to be attributed to mRNA down-regulation and the rapid proteasomal degradation of MOAP-1 that could be reversed utilizing the proteasome inhibitor MG132." (PMID 26269600, 2015). "Currently, the mechanism responsible for the loss of MOAP-1 expression in cancer cells remains unknown." (PMID 22745908, 2012). "Although loss of RASSF1A expression is frequently observed in human cancers, it is currently unknown if MOAP-1 expression may also be affected during carcinogenesis to result in uncontrolled malignant growth." (PMID 22745908, 2012). "This study overcomes these limitations by establishing a sensitized 3D spheroid cancer cell model that employs the adenovirus-mediated gene expressions of tumor-suppressor and pro-apoptotic genes consisting of MOAP-1, BAX, and RASSF1A." (PMID 41874166, 2026). "Previous studies have revealed that MOAP1 (PNMA4) likely plays a role in regulating apoptosis, but beyond these studies in cancer cell lines, functional studies remain sparse." (PMID 38507667, 2024). "Overexpression of these miRNAs usually inhibits the expression of MOAP1, thus promoting cancer cell proliferation, migration, and invasion." (PMID 35269511, 2022). "For example, it is known that RASSF1A and MOAP1 intimately interact to form the RASSF1A/MOAP1 molecular pathway in cancer." (PMID 35269511, 2022). "In summary, MOAP1 can activate the apoptosis signaling pathway, promoting its role in many diseases, such as cancers and neurological diseases." (PMID 35269511, 2022). "In cancer cells, tricistronic expression of MOAP1, BAX, and RASSF1A (MBR) expression will induce cell death and thus increase chemo-sensitization." (PMID 35269511, 2022). "Our results illustrated that the primary genes responsible for apoptosis including CASP 3, CASP 7, TNF-α, TNF-β, and MOAP1 were significantly upregulated by TIT3 treatment on HepG2 cancer cells." (PMID 31482051, 2019). "Increased expression of miR-92a-3p in CRC cells activates Wnt/β-catenin pathway and inhibits mitochondrial apoptosis by directly inhibiting FBXW7 and MOAP1, contributing to cancer progression and chemotherapy resistance." (PMID 31064356, 2019). "In this study, we have explored the mRNA expression of RASSF1A, MOAP-1 and the well-characterized splice variant of RASSF1, RASSF1C, in cancer cell lines and primary tumors." (PMID 27294960, 2016).